GPNMB (glycoprotein nmb)
Diseases named in the same sentence as GPNMB in open-access papers (continued):
Sharing a sentence is not in itself a finding about the gene and the disease.
Obesity (continued). "In conclusion, our data show that UHRF1 positively regulates 3T3-L1 adipogenesis and limits fibrosis by suppressing GPNMB and TGF-β signaling cascade, highlighting the potential relevance of UHRF1 and its targets to the clinical management of obesity and linked metabolic disorders." (PMID 38789534, 2024). "They further showed that GPNMB was capable of inducing obesity and insulin resistance in mice and this phenotype could be rescued by an anti-GPNMB antibody." (PMID 36875463, 2023). "Furthermore, peptide vaccination against GPNMB eliminated GPNMB-positive senescent cells, reducing atherosclerotic plaque burden and metabolic dysfunction such as glucose intolerance in mouse models of obesity and atherosclerosis." (PMID 38138958, 2023). "Importantly, GPNMB is upregulated in obesity-related NAFLD, exerting beneficial impact by reducing oxidative stress." (PMID 36430499, 2022). "GPNMB is also induced and secreted in white adipose tissue in obesity." (PMID 34054862, 2021). "In this study, we revealed a protective role of GPNMB in obesity-related metabolic disorders largely through reducing macrophage inflammability, and thus GPNMB activation may provide a therapeutic strategy in obesity and diabetes." (PMID 34582891, 2021). "These metabolic phenotypes are exactly opposite to those in GPNMB-KO mice we described in this study and therefore further support a critical interaction of GPNMB with CD44 to elicit its beneficial anti-inflammatory functions to preserve metabolic homeostasis in obesity." (PMID 34582891, 2021). "Hence, the dysregulation of the level of GPNMB seen in obesity and T2D could be a vital factor affecting bone health." (PMID 38790981, 2024). "Therefore, differential contribution of adipocyte-derived and macrophage-derived GPNMB in the protection against obesity-related metabolic disorders remains unclear." (PMID 34582891, 2021). "Therefore, the role of GPNMB in obesity and its-related metabolic disorders was controversial." (PMID 34582891, 2021). "Therefore, the protective role of GPNMB in the obesity-related metabolic disorders might be significant in considerably obese condition but not in mild obese condition." (PMID 34582891, 2021). "For instance, liver-derived GPNMB binds to the CD44 receptor on white adipose tissue, leading to an increase in lipogenesis via the CD44-PI3K-mTORC pathway and resulting in obesity and insulin resistance." (PMID 38585871, 2024). "Similar findings have been reported for GPNMB and LGR1, which were shown to mediate obesity and insulin resistance by promoting lipogenesis." (PMID 38196046, 2024). "Elevated circulating levels of GPNMB, secreted by the liver, induced lipogenesis in WAT-exacerbating-diet-induced obesity and insulin resistance." (PMID 38790981, 2024). "This study is the first to report that UHRF1 modulates adipogenesis through GPNMB and TGF-β activation, and it highlights the significance of studying UHRF1 and its targets as a potential therapeutic approach to obesity preventive healthcare." (PMID 38789534, 2024). "In this study, we identified that GPNMB is highly expressed in macrophages and hypertrophied adipocytes, and that it plays crucial role in the WAT inflammation during obesity." (PMID 34582891, 2021). "On the other hand, there was a report that GPNMB secreted from liver promotes lipogenesis in WAT and aggravates diet-induced obesity and insulin resistance." (PMID 34582891, 2021). "Also, the robust increase of GPNMB in mature adipocytes during obesity suggests an involvement of GPNMB in obesity-related adipocyte dysfunction, while the high GPNMB expression in the SVF might reflects the infiltration of macrophages in the WAT during obesity." (PMID 34582891, 2021). "The GPNMB is a promising biomarker and therapeutic target for the development and progression of NAFLD in obesity." (PMID 26581806, 2015).
Obesity (continued). "In the patients with NASH, soluble GPNMB concentrations in sera were higher compared with the patients with SS and soluble GPNMB is a promising biomarker and therapeutic target for the development and progression of NAFLD in obesity." (PMID 26581806, 2015). "The soluble GPNMB is suggested to have an opposite effect, stimulating lipogenesis in white adipose tissue (WAT), resulting in a positive correlation between soluble GPNMB and obesity." (PMID 38790981, 2024). "In one report, it has been shown that target activation of GPNMB in adipocytes ameliorated the fat accumulation and fibrosis of the liver in diet-induced obesity model without affecting the adiposity and glucose metabolism." (PMID 34582891, 2021). "Our current study using the GPNMB-KO mice clearly showed that GPNMB plays a protective role against obesity-related metabolic disorders without affecting obesity and/or adiposity." (PMID 34582891, 2021). "Recently, it has been reported that GPNMB expressed in adipocytes ameliorated the fat accumulation and fibrosis of the liver in diet-induced obesity model without affecting obesity and adiposity." (PMID 34582891, 2021). "One such protein termed a ‘seno-antigen’, glycoprotein nonmetastatic melanoma protein B (GPNMB), was formulated into a senolytic vaccine and injected into progeroid mice, effectively reducing SC burden, alleviating pathological effects of obesity and atherosclerosis, and extending lifespan." (PMID 38076538, 2023). "Considering the remarkable induction of GPNMB in adipocytes of obese mice, we presume that abundantly produced soluble GPNMB-ECD by hypertrophied adipocytes might play some roles in the inhibition of WAT inflammation during obesity, though further analyses are required to elucidate this issue." (PMID 34582891, 2021). "Also, the supplementation with betaine and miR-143 knockout caused obesity attenuation due to the repression of the glycoprotein nonmetastatic melanoma protein B (GPNMB), which has been reported to promote lipogenesis in white adipose tissue (WAT) and intensify diet-induced obesity." (PMID 38003013, 2023).
triple-negative breast carcinoma (14 papers, 2015 to 2025). An invasive breast carcinoma which is negative for expression of estrogen receptor (ER), progesterone receptor (PR), and human epidermal growth factor receptor 2 (HER2). "The METRIC study (NCT#0199733) explored a novel antibody–drug conjugate, glembatumumab vedotin (GV), targeting gpNMB that is overexpressed in ~40% of patients with triple-negative breast cancer (TNBC) and associated with poor prognosis." (PMID 34016993, 2021). "Glembatumumab vedotin is an antibody–drug conjugate derived from dolastatin 10 that targets transmembrane glycoprotein NMB (GPNMB) in GPNMB-positive metastatic triple-negative breast cancer." (PMID 40278278, 2025). "GPNMB promotes cancer cell stemness and metastasis, and its expression is triggered by standard chemotherapy agents in triple-negative breast cancer." (PMID 39685635, 2024). "Conversely GPNMB, a migration-related gene, is frequently overexpressed in triple negative breast cancer among others." (PMID 26620706, 2015). "In addition, GPNMB is a prognostic indicator and is assessed to identify recurrence in triple-negative breast cancers." (PMID 35678671, 2022). "Lastly, PET imaging of gpNMB could be applied to other cancer types that overexpress this clinically-relevant target beyond triple negative breast cancer." (PMID 29262642, 2017). "High levels of expression of glycoprotein non-metastatic B (gpNMB) in triple negative breast cancer (TNBC) and its association with metastasis and recurrence make it an attractive target for therapy with the antibody drug conjugate, glembatumumab vedotin (CDX-011)." (PMID 29262642, 2017). "In triple-negative breast cancer (TNBC), GPNMB overexpression correlates with poor prognosis and demonstrates therapeutic vulnerability, as evidenced by CDX-011 (anti-GPNMB ADC) achieving 40% objective response rates." (PMID 41180454, 2025). "Glenmabusumab-vedotin demonstrated encouraging efficacy in treating triple-negative breast cancer (TNBC) in the CR011-CLN-20 study and the ensuing EMERGE analysis, especially in patients whose tumors overexpress gpNMB (glycoprotein NMB)." (PMID 39456611, 2024). "Glycoprotein non-metastatic B (GPNMB) is a transmembrane protein overexpressed in numerous cancers including triple-negative breast cancers (TNBC)." (PMID 34108545, 2021).
osteosarcoma (10 papers, 2020 to 2025). A usually aggressive malignant bone-forming mesenchymal neoplasm, predominantly affecting adolescents and young adults. "In view of this important finding, the feasibility of developing new therapeutic drugs or treatment regimens targeting GPNMB has begun to be explored, bringing new hope for the future treatment of osteosarcoma." (PMID 41180454, 2025). "When a comparative analysis was conducted between osteosarcoma tissues and normal tissues, it was found that the mRNA level and protein level of GPNMB in osteosarcoma tissues were both significantly upregulated compared with those in normal tissues." (PMID 41180454, 2025). "GPNMB may also be a potential target for targeted therapy of osteosarcoma, as it has been found that GPNMB can regulate the metastasis and proliferation of osteosarcoma cells by affecting the PI3K/AKT/mTOR pathway." (PMID 37404761, 2023). "Furthermore, silencing of GPNMB has been shown to reduce the proliferation of osteosarcoma cells through suppressing mTOR signaling." (PMID 34445242, 2021). "GPNMB as a therapeutic target has not been explored in the field of neurodegeneration, but in oncology, GPNMB has been used as a therapeutic for osteosarcoma and squamous cell carcinoma, but the efficacy of this therapy is questionable." (PMID 38037070, 2023). "Proteins that are overexpressed on osteosarcoma cells, such as the glycoprotein non-metastatic B (GPNMB), the leucine-rich repeat-containing 15 (LRRC15), B7-H3, GD2, and HER2, could represent potential targets for ADCs." (PMID 37109122, 2023). "GPNMB (glycoprotein non-metastatic b) is a transmembrane glycoprotein normally expressed in cells related to tissue repair, and it is overexpressed in some malignant cells including osteosarcoma." (PMID 35408900, 2022). "The monoclonal antibody glembatumumab vedotin (GV) targets a type I transmembrane glycoprotein, named glycoprotein non-metastatic B (gpNMB), which enhances cellular growth and metastatic potential, and has been found to be frequently overexpressed in osteosarcoma cells." (PMID 33917001, 2021). "Glycoprotein nonmetastatic B (gpNMB) is a type I transmembrane glycoprotein expressed in normal cells involved in tissue repair, adhesion, and growth, and its overexpression has been found in several cancers including osteosarcoma." (PMID 32961800, 2020).
gastric cancer (9 papers, 2011 to 2024). A primary or metastatic malignant neoplasm involving the stomach. "A previous study also found that the HDAC inhibitor, trichostatin A, induced apoptosis by inhibiting GPNMB expression in gastric cancer." (PMID 35678671, 2022). "GPNMB is highly expressed in gastric cancer tissue compared with normal tissues suggesting that the TSA effect against gastric cancer could be mediated by the downregulation of GPNMB." (PMID 36297347, 2022). "Moreover, GPNMB exhibits diverse regulatory effects on gastric cancer-mediated immunosuppression." (PMID 38239355, 2023). "In gastric cancer, CSE1L inhibition has been shown to activate the PI3K/AKT/mTOR and MEK/ERK pathways by downregulation of MITF and GPNMB." (PMID 39430746, 2024). "GPNMB was expressed in four of six breast cell lines (SK-BR-3, BT-474, MDA-MD-231, and MDA-MD-157), two of six colorectal cell lines, and two of four gastric cancer (GC) cell lines." (PMID 26077887, 2015). "In gastric cancer cells, TSA induced apoptosis and cell cycle arrest, which was associated with a significant decrease in glycoprotein non-metastatic melanoma protein B (GPNMB) expression." (PMID 36297347, 2022).
lysosomal storage disorders (9 papers, 2017 to 2024). "The expression of GPNMB is up-regulated in several lysosomal storage diseases and is correlated with lipid accumulation in the lysosome." (PMID 34103390, 2021). "Lysosomal storage disease genes include GRN, GPNMB, GAA, and CHIT1 which, according to STRING analyses, interact with CD68, CD63, and TLR3, and are known to have lysosomal membrane function." (PMID 37422510, 2023). "One such gene is GPNMB (osteoactivin), encoding transmembrane glycoprotein non-metastatic melanoma protein B, which is induced upon MiT activation and is mainly expressed in melanocytes, osteoclasts, dendritic cells and overexpressed in various cancers and lysosomal storage disorders." (PMID 35842725, 2022).
prostate carcinoma (8 papers, 2018 to 2025). A carcinoma that arises from epithelial cells of the prostate gland. "During the screening of genes related to the metastasis and invasion of prostate cancer, abnormal expression of GPNMB was found." (PMID 41180454, 2025). "For instance, in prostate cancer, GPNMB significantly inhibits cell proliferation and invasion by enhancing the expression of Ndrg1 and maspin genes." (PMID 39263169, 2024). "The expression of GPNMB in prostate cancer cell lines and animal models results in the activation of N-myc downstream-regulated gene 1 (Ndrg1) in-vitro and in-vivo." (PMID 30400781, 2018). "This indicates that in prostate cancer, GPNMB may reduce the degradation of cancer cells by affecting P75NGFR, thereby promoting their proliferation." (PMID 41180454, 2025). "They suggested that GPNMB plays a key role as tumor suppressor in prostate carcinoma cells." (PMID 30400781, 2018). "Prostate cancer experimental data also demonstrated a tumor suppressor activity for GPNMB." (PMID 30400781, 2018). "In prostate cancer cells DU145 and PC3 with high expression of GPNMB, exogenous addition of nerve growth factor (NGF) can induce the regeneration of the NGF receptor P75NGFR, and P75NGFR is related to the degradation of cancer cells." (PMID 41180454, 2025). "This phenomenon is also documented in other types of cancer, as GPNMB promotes the invasion and proliferation of prostate cancer cell lines through the activation of MMP-2 and MMP-9, which can be reversed by GPNMB knockdown by siRNA transfection." (PMID 34054862, 2021).
atherosclerosis (7 papers, 2022 to 2025). A disease characterized by the build-up of fatty material and calcium deposition in the arterial wall resulting in partial or complete occlusion of the arterial lumen. "Another vaccination strategy targets GPNMB, a senescence-associated transmembrane protein enriched in vascular endothelial cells and leukocytes during atherosclerosis." (PMID 40666427, 2025). "Immunization against GPNMB reduced senescent cell burden, improved metabolic function, and alleviated atherosclerosis in high-fat diet-fed and ApoE-deficient mice." (PMID 40666427, 2025). "Suda and coworkers demonstrated that GPNMB expression is upregulated in the case of atherosclerosis in vascular endothelial cells and leukocytes." (PMID 38138958, 2023). "Mice with apolipoprotein E knockout, a murine model of atherosclerosis (age-related disease), accumulate senescent cells; when these mice were treated with anti-GPNMB, senescence was attenuated, and aging progression was slower than that of unvaccinated mice." (PMID 36835661, 2023). "GPNMB presents a transmembrane domain considered a seno-antigen that localizes to vascular endothelial cells in humans and mice with atherosclerosis." (PMID 36835661, 2023). "GPNMB is upregulated in the aorta and adipose tissues of aged and obese mice, as well as in the aortae of an atherosclerosis mouse model." (PMID 37174697, 2023). "GPNMB expression was significantly upregulated in vascular endothelial cells of patients and mice with atherosclerosis." (PMID 35444208, 2022). "Interestingly, a senolytic vaccine targeting GPNMB alleviated diabetes and atherosclerosis-related complications in mouse models." (PMID 37174697, 2023). "They demonstrated that vaccination against GPNMB in the male premature ageing model mice extended their lifespan by 5.4 weeks, mainly eliminated the Gpnmb-positive senescent cells, and attenuated age-related pathologies such as atherosclerosis and metabolic abnormalities." (PMID 39263169, 2024).
colorectal cancer (7 papers, 2015 to 2024). A primary or metastatic malignant neoplasm that affects the colon or rectum. "Previous investigations utilizing whole-exome sequencing analysis have also reported higher GPNMB expression in patients of colorectal cancer (CRC) with liver metastasis than paired primary CRC, and its association with poor prognosis." (PMID 38706915, 2024). "Another study showed that higher methylation profile of GPNMB led to a lower expression in adenoma and colorectal cancer samples." (PMID 35486660, 2022). "Our present methylation results showed a statistically significant difference in the frequency of GPNMB promoter methylation between colorectal cancer and normal colon mucosa." (PMID 30400781, 2018). "Taken together, these data suggest that GPNMB exhibits tumor suppressive effects in human colorectal cancer cells." (PMID 30400781, 2018). "We measured serum GPNMB in vivo in 162 consecutive BC patients and in 88 controls (50 colorectal cancer [CC] and 38 GC patients)." (PMID 26077887, 2015). "The methylation status of 13 CpG promoter sites (chr7: 23287345–23,287,426) in GPNMB was measured by pyrosequencing using primers designed by EpigenDx primers were first tested on three human colorectal cancer cell lines (HCT116, HT29, and SW480) and one male normal blood DNA by pyrosequencing." (PMID 30400781, 2018). "The difference of GPNMB methylation in advanced adenoma and colorectal cancer tissues was not statistically significant (42/48 [88%] vs. 18/20 [90%]; P = 0.88)." (PMID 30400781, 2018).